AKT1 (AKT serine/threonine kinase 1)
Diseases named in the same sentence as AKT1 in open-access papers (continued):
Sharing a sentence is not in itself a finding about the gene and the disease.
Hyperglycemia (151 papers, 2012 to 2026). An increased concentration of glucose in the blood. "In the treatment of DW, the activation of AKT1 promotes cell growth and repair and inhibits apoptosis and oxidative stress induced by hyperglycemia." (PMID 40225010, 2025). "Although clinical AKT-targeting inhibitors have been developed for treating AKT1 mutation-related cancers, they often target multiple AKT variants (AKT1, AKT2, and AKT3) and cause side effects like hyperglycemia, limiting their clinical usefulness." (PMID 40478506, 2025). "In this study, it was observed that the pathological damage associated with hyperglycemia and suppression of lncRNA MEG3 increased the inflammatory response and decreased the expression levels of genes involved in the PI3K/AKT1 pathway." (PMID 40869265, 2025). "In contrast, systemic deletion of Akt1 or Akt2 in mice increases mortality, due to significant disruptions in circulating glucose and insulin levels, resulting in hyperglycemia, which is notably a known adverse effect of pan-AKT inhibitors in the clinic." (PMID 33105713, 2020). "The essential role of DCs as CD137L producers in vivo was definitively established through lineage-specific Akt1 deletion, which abrogated CD137L expression in DCs and reversed the adverse effects of hyperglycemia on increased IL-17+ T cells and loss of Tregs in vivo." (PMID 41379565, 2025). "Baicalin is the main component found in Scutellaria baicalensis root, an herb widely used in traditional Chinese medicine, which can alleviate hyperglycemia-induced endothelial impairment by downregulating ROS and inflammation via the AKT1/GSK3B/FYN-mediated NRF2 activation." (PMID 35204118, 2022). "Research indicates that Akt1 is capable of regulating Slc2a2 transcription in liver tissues, strengthening the liver’s capacity to uptake glucose from the circulation, facilitating cellular energy metabolism, and optimizing glucose utilization efficiency, consequently diminishing hyperglycemia." (PMID 41517209, 2026). "We found that AKT1 is consistently downregulated in AD as well as in T2DM, which supports the fact that glucose levels are increased in blood, a condition called hyperglycemia." (PMID 28922161, 2017). "Inactivation of liver PI3K, AKT1, or AKT2 could induce hyperglycemia and hyperinsulinemia." (PMID 32280711, 2020).
leukemia (146 papers, 2006 to 2026). A malignant (clonal) hematologic disorder, involving hematopoietic stem cells and characterized by the presence of primitive or atypical myeloid or lymphoid cells in the bone marrow and the blood. "Excessive Akt activity in thymocytes due to PI3K hyperactivity, Pten inactivation or dominant-active Akt1 expression causes leukemia/lymphoma." (PMID 26880557, 2016). "Tumours samples from the patients with breast, colorectal cancer and cases of leukaemia has been shown to frequently harbour activating somatic mutations in AKT1." (PMID 23741320, 2013). "This mutation (E17K) increases recruitment of AKT1 to the membrane, increases AKT1 phosphorylation and activity, transforms Rat1 fibroblasts, and induces leukaemia in transgenic mice." (PMID 18813315, 2008). "Point mutation in AKT1 has been detected in Proteus syndrome, endometrial carcinomas and leukaemia, gene amplification in a single gastric carcinoma out of a screen of more than 225 diverse human malignancies, and in 1 gliosarcoma out of 103 malignant glial cancers." (PMID 23741320, 2013). "Functionally, the AKT1 E17K mutation stimulates AKT signalling, induces cellular transformation and produces leukaemia in mice, strongly suggesting that this mutation may play a crucial role in cancer development." (PMID 18392055, 2008). "Moreover, Following HMGCR inhibition with pitavastatin treatment, an attenuated oncogenic AKT1 signaling was evident along with the suppression of MYC signaling pathway expression via the loss of chromatin accessibility at the leukemia stem cell-specific long-range MYC enhancer." (PMID 37745085, 2023). "We analyzed the expression of the PIK3CA, AKT1, and mTOR genes across various leukemia cell lines using the Human Protein Atlas database, with a specific focus on the HL-60 cell line, which was employed in our study." (PMID 40917720, 2025). "Since AKT1 is hyperactivated in many cancers including leukemia, it is a potential signature of DAV resistance." (PMID 38161214, 2024). "In leukemia, AKT1 and AKT2 phosphorylate PHB2 at S91, regulate nuclear-mitochondria activity, and further promote cell survival." (PMID 37190120, 2023). "The only known function of Tcl1 protein is to enhance the kinase activity of Akt1 (thymoma viral proto-oncogene 1) in leukemia cells." (PMID 17183653, 2006). "Given that ID1 promotes AKT1 phosphorylation through its C-terminal region without disrupting its interaction with bHLH, combined targeting of ID1 and AKT1 might be a promising therapeutic strategy for leukemia." (PMID 41146039, 2025). "This ribosomal protein is phosphorylated at the S106 residue by AKT1 in leukemia cells." (PMID 40497989, 2025). "AML patients frequently show increased AKT1 activity, providing leukemic cells with growth and survival promoting signals and enhanced AKT activation has been implicated in the transformation from MDS to AML and overexpression of AKT has been shown to induce leukemia in mice." (PMID 34220922, 2021). "It is interesting to detect the TCL6 in leukemia-specific MAEs, since it was recently reported that low TCL6 levels were associated with poor survival of B-cell ALL patient, through a link between TCL6, TCL1B, and the AKT1 pathway." (PMID 34722498, 2021). "The E17K change results in constitutive AKT1 activation, induces leukaemia in mice, and accordingly, may be therapeutically exploited to target the PI3K pathway." (PMID 19461960, 2009). "A subsequent study investigated whether a HL-60 human leukemia cell clone (named AR) with constitutively active Akt1 was resistant to TRAIL." (PMID 19384426, 2007). "Several PI3K/AKT/MTOR pathway genes were identified to affect cell proliferation in the shRNA screen (e.g. PIK3CD, AKT2, AKT1, RPS6) confirming our previous data about PI3K/AKT/MTOR activation in mouse E2A-PBX1+ leukemia cells." (PMID 35794338, 2022).
leukemia (continued). "AKT1 and AKT2 both interact with all TCL1 family members like TCL1, MTCP1, and TCL1b in leukemia cells and as consequence the activity of both isoforms is increased in an unspecific manner." (PMID 31752925, 2019). "Immunoprecipitation results showed that FAM168A interacts with breakpoint cluster region (BCR) -Abelson murine leukemia (ABL1) fusion protein and AKT1, respectively." (PMID 31291942, 2019). "The discovery of AKT dates back to the 1970s, when an oncogene sequence, named AKT8, was identified in murine leukemia viruses, and two homologous oncogenes of AKT8, named AKT1 and AKT2 (also known as PKKB αand PKKB β, respectively), were subsequently identified in human chromosomes." (PMID 36579349, 2022). "HSP90 has been shown to regulate the activation of AKT1 and ERK in leukemia and esophageal SCC." (PMID 35095481, 2021). "In the pediatric setting, the PI3K/AKT/mTOR signaling axis has been described as abnormally activated in both hematologic and solid tumors, mainly as a consequence of chromosomal gains amplifying the AKT1 gene (described in rare cases of leukemia) or the aberrant expression of PI3K isoforms." (PMID 36839989, 2023).
endometrial cancer (138 papers, 2009 to 2026). Primary or metastatic malignant neoplasm involving the endometrium (mucous membrane that lines the endometrial cavity). "AKT1, an intracellular kinase, is frequently subject to mutation in various cancer types, including breast and endometrial carcinomas." (PMID 41142752, 2025). "The L52R mutation in AKT1 was detected in endometrial cancer, and D323G in BC that is ER positive and HER2-negative." (PMID 39138146, 2024). "The frequency of AKT1 mutations in endometrial cancer was 4.1%, and the mutations were histologically detected only in endometrioid types." (PMID 34670536, 2021). "The clinicopathological features and frequencies in Asian populations with AKT1 mutations in breast and endometrial cancers are unclear." (PMID 34670536, 2021). "We extracted DNA from 311 and 143 samples derived from patients with breast and endometrial cancers to detect the AKT1 point mutation (hotspot), E17K." (PMID 34670536, 2021). "This is the first report of an association between clinicopathological features and AKT1 mutation status in women with breast and endometrial cancers in Asia." (PMID 34670536, 2021). "Six patients initially had metastatic lesions, 18 of the 137 patients who initially had early endometrial cancer, relapsed (16 and 2 patients with wild-type and mutated AKT1, respectively), and 21 patients died of any cause." (PMID 34670536, 2021). "Here, we investigated the frequencies of AKT1 mutations and their associations with clinicopathological features in Asian women with breast and endometrial cancers." (PMID 34670536, 2021). "The frequencies of AKT1 mutations in breast and endometrial cancers were similar between Asian and other regional women." (PMID 34670536, 2021). "In the present study, we found AKT1 mutations in 7.3 and 4.1% of breast and of endometrial cancer samples." (PMID 34670536, 2021). "The transforming somatic mutation of Glu 17 to lysine (E17K) in AKT1 has been reported in several cancers including human breast, colorectal, ovarian and endometrial cancers." (PMID 20886116, 2010). "We analysed the presence of the AKT1 (E17K) mutation in 89 endometrial cancer tissue specimens and in 12 endometrial cancer cell lines by PCR and direct sequencing." (PMID 19491896, 2009). "Indeed, Akt1 deficiency is sufficient to inhibit the development of endometrial carcinoma in PTEN+/− mice." (PMID 26468779, 2015). "In this study, we screened 89 endometrial carcinoma specimens and 12 endometrial carcinoma cell lines for mutations in Akt1 (E17K) and analysed whether AKT1 mutations coexist with any mutations in PTEN, PIK3CA and K-Ras." (PMID 19491896, 2009). "Furthermore, higher AKT1 expression is associated with poor prognosis for endometrial cancer." (PMID 40282476, 2025). "In addition, AKT1 mutations were found in atypical hyperplasia, suggesting that AKT1 mutations may be involved in the carcinogenesis of endometrial carcinoma in benign and (pre) malignant endometrial lesions." (PMID 34670536, 2021). "Therefore, these hub genes associated AKT1 may serve as important roles in the pathogenesis of endometrial cancer." (PMID 31781484, 2019). "The AKT inhibitor capivasertib has been studied in AKT1 E17K–mutant solid tumors, with responses in cervical, breast, lung, and endometrial cancers." (PMID 38938274, 2024). "Likewise, AKT1-rs2498794 may increase the risk of endometrial cancer." (PMID 36152082, 2023). "Miransertib is an AKT1 inhibitor that has been combined with anastrozole in women with PIK3CA and AKT1-mutant ER-positive endometrial cancer and EOC." (PMID 37626654, 2023). "An AKT1 L52R-mutant endometrial cancer patient had a durable partial response (PR) lasting nearly a year." (PMID 35440569, 2022). "In summary, our results demonstrated that FBXL16 promoted MPA resistance of Ishikawa cell by PP2AB55α interaction and AKT1/GSK3β/cyclin D1 pathway in endometrial carcinoma, while knockdown of FBXL16 can reverse the MPA resistance of Ishikawa." (PMID 36106050, 2022).
endometrial cancer (continued). "In endometrial cancer, the activation of AKT1 in adult endometrium was enough to initiate endometrial cancer." (PMID 31781484, 2019). "In this study, we performed a multi-steps analysis to explore the molecular mechanisms of AKT1 in the pathogenesis of endometrial cancer." (PMID 31781484, 2019). "We selected the six hub genes (GTSE1, BIRC5, AURKA, PBK, KNSTRN, and PSMB10) and AKT1 to evaluate gene expression values in endometrial cancer using IHC." (PMID 31781484, 2019). "Due to the high mutation rate of PTEN in ovarian and endometrial cancers, PI3K is unrestrained, leading to a high AKT1 phosphorylation and subsequent inhibition of Par-4 activity which is related to chemoresistance." (PMID 27175591, 2016). "Most significantly, in an in vivo study, ARQ 092 and ARQ 751 showed strong anti-tumor activity against a homologous AKT1 mutant (AKT1-E17K) endometrial cancer patient-derived xenograft (PDX) model." (PMID 26469692, 2015). "Association and functional analyses have demonstrated that the SNP rs2494737 maps to this silencer element, affecting its regulatory capability over the AKT1 promoter, hence resulting in increased AKT1 expression in both Ishikawa and EN-1078D endometrial cancer cells." (PMID 35011637, 2021). "Moreover, in a recent study on endometrial cancer, it was found that the expression of KNSTRN was positively correlated with AKT1, and high expression of KNSTRN was significantly associated with poor prognosis of endometrial cancer." (PMID 33976733, 2021). "In addition, the data also shows that the higher expression of AKT1, GTSE1, BIRC5, AURKA, and KNSTRN is significantly associate with poor prognosis of endometrial cancer." (PMID 31781484, 2019). "In conclusion, after a comprehensive analysis of the data of endometrial cancer patients, we have identified a set of hub genes that were regulated by AKT1 and may serve as potential biomarkers for prognosis prediction of endometrial cancer patients." (PMID 31781484, 2019). "In present study, we have performed a multi-steps bioinformatics analysis in endometrial cancer using the gene expression profiles from GEO database and identified a set of genes that may be regulated by AKT1." (PMID 31781484, 2019). "Moreover, the data also shows that the higher expression of AKT1, GTSE1, BIRC5, AURKA, and KNSTRN is significantly associate with poor prognosis of endometrial cancer." (PMID 31781484, 2019). "In this study, by integrating different bioinformatic methods, and analyzing clinical information and gene expression profiles of endometrial cancer patients, we aim to investigate the potential mechanisms of AKT1 in the tumor progression of endometrial cancer." (PMID 31781484, 2019). "A specific endometrial cancer organoid line was most sensitive to everolimus (an inhibitor of mammalian target of rapamycin mTOR), which suggested a strong dependence on the PI3K-AKT pathway and was in line with mutations in the pathway’s signaling mediators (PTEN, PIK3CA, AKT1)." (PMID 36699015, 2022). "However, the clinicopathological features and mutation frequency of AKT1 in Asian populations with breast and endometrial cancers have not been examined." (PMID 34670536, 2021). "However, AKT1 mutations did not correlate with relapse-free or overall survival of patients with breast or endometrial cancer." (PMID 34670536, 2021). "Additional co-expression analysis studies have shown that AKT1, TICRR, PPIF, ANO1, and PTGDS are possible regulators of endometrial cancer tumorigenesis." (PMID 39596419, 2024). "In addition to the patient with endometrial cancer who met the CBR definition of SD (>6 months), a second patient with AKT1 E17K mutant endometrioid endometrial carcinoma had target lesion reduction (−19%) and remained on study for 6 cycles with SD." (PMID 31303643, 2019).
endometrial cancer (continued). "Lastly, we identified a human endometrial cancer cell line with a kinase domain mutation in AKT1 (G311D) that failed to induce phosphorylation of endogenous AKT substrates in AKT1/2 DKO HCT116 cells." (PMID 25551293, 2014). "Furthermore, investigations into specific compounds, such as kaempferol and quercetin, suggest their role in modulating PPARG expression and interacting with AKT1, pointing towards potential treatment avenues for endometrial cancer and nonsegmental vitiligo." (PMID 38505269, 2024).
meningioma (130 papers, 2013 to 2026). A generally slow growing tumor attached to the dura mater. "His pathology showed that he had a WHO Grade I meningioma with an AKT1(E17K) mutation identified on molecular profiling." (PMID 41515621, 2026). "Mutations in PIK3CA and AKT1 are frequent in meningiomas, whereas activating mutations affecting the RAS/RAF/MEK/ERK, PI3K/AKT, and Wnt pathways have been described in pituitary adenomas." (PMID 41514664, 2026). "The AKT1 variant AKT1E17K found in meningiomas activates the mTOR signaling pathway, which promotes cell growth, survival, and proliferation while inhibiting apoptosis." (PMID 41372821, 2025). "SMO, a G-coupled receptor, is important in the Hedgehog signaling pathway, which is crucial in promoting angiogenesis and tumor progression, and is linked with larger meningiomas and a higher recurrence rate than that in AKT1-mutated meningiomas." (PMID 39202270, 2024). "The AKT1 E17K mutation is a known oncogenic alteration which was detected in about 8–13% of meningiomas, especially those located in the skull base where 31% of tumors were found to display this alteration." (PMID 36181606, 2023). "Like TRAF7/KLF4-mutated meningiomas, also AKT1-mutated tumors are frequently found in the skull base." (PMID 36181606, 2023). "The intronic mutation of the AKT1 gene detected in the tumor of the present study (in c.175+18C>T) was also previously reported in meningioma tumors (COSN17133117)." (PMID 37273678, 2023). "The most significant gene overexpressed in KLF4 meningiomas relative to AKT1 meningiomas was tetraspanin TSPAN12, which encodes a member of the transmembrane 4 superfamily." (PMID 36937440, 2023). "SFRP-1 for instance, has been shown to be upregulated in AKT1(E17K) activating mutation which predominantly appears in WHO 1 meningiomas." (PMID 38023177, 2023). "Another study in 300 grades 1 and 2 meningiomas has found that 13% harbored the AKT1 p.Glu17Lys mutation and displayed immunohistochemical evidence of PI3K–AKT–mTOR pathway activation." (PMID 35565385, 2022). "SMO, PI3KCA and AKT1-mTOR mutations are typically found in WHO grade 1 meningiomas with a high rate of recurrence." (PMID 35892898, 2022). "It was found that WHO grade 1 meningiomas with an AKT1 mutation predominantly had M2 macrophages, which results in a locally immunosuppressed tumor microenvironment." (PMID 35453901, 2022). "NF2-altered tumors are mainly localized at the convexity or in the lateral and posterior skull base; SMO-mutated meningiomas arise in the olfactory groove, while those with AKT1 and PIK3CA mutations are mostly found in the anterior and middle skull base." (PMID 35049691, 2022). "Compared to meningiomas with AKT1 mutations, SMO-mutated olfactory groove meningiomas had higher recurrence rates, and when compared to AKT1-mutated or wild type meningiomas, SMO-mutated anterior skull base meningiomas had significantly larger tumor volume." (PMID 36686824, 2022). "In a study that applied exome sequencing to 300 meningiomas, mutations in AKT1 were found in 13% of tumors." (PMID 36686824, 2022). "Studies have found predominantly immunosuppressive type macrophages in AKT1 mutated meningiomas, while NF2 gene mutated tumors have high levels of immune active macrophages." (PMID 36033542, 2022). "Meningiomas with an AKT1 E17K mutation harbored additionally ATRX (n = 2), ARID1A (n = 2), TRAF7 (n = 1) and POLR2A (n = 1)." (PMID 35943573, 2022). "Other mutations in previously documented genes associated with meningiomas, including AKT1 (one missense and one splice site variants) and TRAF (five missense and one splice site variants), were also found." (PMID 35774130, 2022).